IL2 (interleukin 2)
Diseases named in the same sentence as IL2 in open-access papers (continued):
Sharing a sentence is not in itself a finding about the gene and the disease.
asthma (continued). "This includes more Th1 cytokines (IFN-γ and IL-2) combined with fewerTh2 cytokines (IL-4 and IL-5), correlated with significantly higher NK cell cytotoxicity as compared to the asthma group." (PMID 33919400, 2021). "In a very small study in children with severe asthma (n = 8), IL-2, MCP-1, and two markers of airway remodeling (platelet-derived growth factor BB and tissue inhibitor of metalloproteinase 2) showed a good correlation with fractional exhaled nitric oxide (FeNO)." (PMID 31106182, 2019). "Collectively, our results suggest that an environment of high IL‐2 may mediate asthma severity by dampening GC responsiveness, resulting in persistence of Th2 cells and production of type 2 cytokines." (PMID 30994266, 2019). "This study investigated the activity of distinct NS preparations on asthma-related targets such as the release of IL-2, IL-6, and PGE2 from peripheral mononuclear human blood cells and a human epithelial cell line (A549) to provide the basis of a clinical study." (PMID 30333747, 2018). "This suppressive effect on IL-2 release from T lymphocyte cells may be beneficial in the context of asthma as it is considered a pro-inflammatory mediator and found in a high level in BALF of patients with asthma." (PMID 30333747, 2018). "Our study suggests that intratracheal treatment with glucocorticoid combined with IL-2 is a safe and effective pharmacological manipulation in asthma therapy in mice and could potentially be used in humans." (PMID 27527926, 2016). "The IL-2:anti-IL-2 treatment is dependent on Treg-derived IL-10, and suggests that endogenous Treg therapy may be a useful tool to combat asthma." (PMID 24886492, 2014). "In severe asthma, Tbet expression was strongly correlated with Il2, Il6, and Il10 expression." (PMID 23781124, 2013). "Our study showed higher basal IL-2 and IL-4 production in PBMCs from severe asthma which could result in p38MAPK activation and subsequent loss of corticosteroid sensitivity." (PMID 22911818, 2012). "IL-2 mRNA levels are increased in the BAL of steroid resistant patients with asthma." (PMID 22417244, 2012). "CD4+ NKT cells may also have a critical role in the pathogenesis of asthma and produce IL-5 when co-cultured with CD1d+ antigen presenting cells and IL-2." (PMID 21423619, 2011). "The gene encoding pro-inflammatory cytokines such as IL-1, IL-2, IL-6, Tumor necrosis factor (TNF)-α, and Monocyte chemoattractant protein (MCP)-1 play significant roles in increasing the risk of chronic diseases such as asthma, atherosclerosis, and rheumatoid arthritis." (PMID 38164478, 2024). "CTCF was also found to be recruited in asthma risk-related SNPs of the ORMDL3 gene and increased the activity of its enhancer in naïve CD4 T cells, which was essential for the repression of Il2 expression in the same cell type, a mechanism that may contribute to asthma progression." (PMID 35812421, 2022). "However, only IL-1β and IL-2 had the same changing trend between asthma and ACO groups." (PMID 36311545, 2022). "Analyzing the whole population together, IL‐2 production was inversely correlated with FEV1 (r = −0.558, P = 0.0162) and positively correlated with total daily dose of inhaled corticosteroid (r = 0.561, P = 0.0155), suggesting its association with asthma severity." (PMID 30994266, 2019). "Moreover, patients treated with inhaled IL-2 had asthma-like signs and symptoms." (PMID 30333747, 2018). "Similarly, as circulating lymphocytes from asthma patients also produce large amounts of interleukins, including IL-2, -4, and -5, the authors hypothesized that asthma may be a risk factor for temporomandibular joint osteoarthritis." (PMID 29385182, 2018). "Thus, IL-2 and IL-4 are likely to be responsible for reduced corticosteroid responsiveness as both cytokines were increased in severe asthma and induced corticosteroid insensitivity in vitro via reduced GR nuclear translocation due to excessive GR serine 226 phosphorylation." (PMID 22911818, 2012).
asthma (continued). "According to our recent real-world findings, tezepelumab rapidly diminished the serum levels of interleukin-2 (IL-2) and VEGF in patients with either T2-high or T2-low severe asthma." (PMID 41321706, 2025). "Our results have confirmed that patients with asthma and obesity have increased levels of circulating inflammatory cytokines such as TNF-α, IL-2, IL-4, and IL-17a despite the basic anti-inflammatory therapy." (PMID 37367676, 2023). "SA ILC2s demonstrated a 100‐fold increased release of IL‐6 following stimulation with IL‐2, IL‐33, IL‐25 and TSLP compared to mild asthma and the controls." (PMID 37114915, 2023). "And asthma patients with high expression of IL1-RL1 had higher level of IFN-γ (p = 0.0359), IL-2 (p = 0.0168) and IL-8 (p < 0.0001)." (PMID 35578178, 2022). "It is an important result, once levels of IL-2 (6D), IFN-ɣ (6E), and IL-10 (6F) in serum of asthma mice were higher than those found in the control group." (PMID 36685604, 2022). "il-10, il-4, il-13, il-17a, il-2, tlr4, tlr9, ccl2, csf2, and vegfα are top 10 hub nodes in the PPI network, so we inquired the expression profiles of these genes in asthma from the GEO database." (PMID 33133221, 2020). "Th1 cells exert a protective effect on asthma through releasing IFN-γ and IL-2, while Th2 cells mainly secrete IL-4, IL-5, and IL-13, and then promote the development of asthma." (PMID 30089474, 2018). "Recently, it has been shown that the treatment of mice with IL-2/anti-IL-2 complex, generated by using JES6-1 antibody, increases the number of Tregs and protects from asthma, experimental autoimmune encephalomyelitis (EAE) and type 1 diabetes." (PMID 28881761, 2017). "We also designed a long-acting polyethylene glycol (PEG)-modified IL-2 and demonstrated that the optimal dosage form is IL-2(PEG) plus budesonide, which can upregulate Treg cells and ameliorate asthma at a lower dose." (PMID 27527926, 2016). "In our previous study, we demonstrated that short-term intraperitoneal use of IL-2 at a dose of 400,000 IU combined with dexamethasone at a corresponding dose of 100 μg per mouse could upregulate Treg cells effectively and alleviate allergic airway disease in an asthma mouse model." (PMID 27527926, 2016). "Based on a fixed ratio (4,000 IU IL-2: 1 μg dexamethasone), we explored the upregulation of Treg cells in BALF from an asthma mouse model at different doses." (PMID 27527926, 2016). "After a 3-day administration of IL-2(PEG) and budesonide in asthma BALB/c mice, the BALF samples were obtained." (PMID 27527926, 2016). "Vice versa, transgenic overexpression of CREMα selectively in T cells results in reduced IL-2 expression, decreased pSTAT5 and IL4R levels and diminished TH2 type cytokines in vitro and in an asthma model in vivo." (PMID 26459392, 2015). "IL-2 can be produced by epithelial cells and eosinophils and increased levels are found in the BALF of patients with symptomatic asthma." (PMID 25161620, 2014). "In mild asthma, Il10 showed the largest change in expression followed by II5, II4, Tnfα, Il6, Il2, Il13, and Ifnγ, respectively." (PMID 23781124, 2013). "IL2, IL4, IL5, IL6, IL13, and TNFαhave been reported to enhance asthma in humans, and Th1 cells have been shown to suppress Th2 cells through the release of IFN-γ." (PMID 23781124, 2013). "As same with IL-2/IL-4 model, PP2A was also significantly phosphorylated at Thr307 in PBMCs of severe asthma." (PMID 22205926, 2011). "Percentage proportions of CD4+ T cell staining positively for IL-2, IL-4, IL-10, IL-13, IFN-γ, and TNF-α in unstimulated whole blood were similar in children with asthma compared to healthy controls." (PMID 21197090, 2010). "The data for IL-2-stimulated accumulation of IL-13+ and IFN-γ+ T cell accumulation were stratified to demonstrate the contributions of gender and asthma on accumulation." (PMID 20667106, 2010).
asthma (continued). "IL-2 immune complexes (IL-2C), composed of IL-2 and the anti-IL-2 monoclonal antibody JES6-1, have been shown to selectively expand Tregs without broadly activating effector cells, with demonstrated therapeutic efficacy in asthma, acute lung injury, and COPD." (PMID 40933988, 2025). "Regarding the EWAS of BDR, the gene-set enrichment analysis revealed enrichment in several pathways relevant to asthma, including IL-5 (FDR = 1.1 × 10−2), IL-2 (FDR = 4.2 × 10−2), Fc epsilon Receptor I signaling pathways (FDR = 3.3 × 10−2), and cellular aging (FDR = 4.2 × 10−2)." (PMID 36979655, 2023). "Interestingly, our data indicate that simultaneous administration of IL-2 and IL-4 in vivo suppressed the severity of not only IL-17-dependent EAE, but also several models of murine asthma in both Th1 and Th2-skewed backgrounds." (PMID 33617447, 2021). "IL-2 and IL-4 in combination suppress the severity of HDM-induced asthma." (PMID 33617447, 2021). "Children with a diagnosis of asthma had an increased percentage of type 2 T cells identified as CD4+CCR4+, which demonstrated increased activation of STAT5 following stimulation with 100 U/ml IL-2 for 10 min." (PMID 32985505, 2020). "IL-2 was elevated in BALF of nonallergic asthma patients; moreover, expression of IL-2 mRNA was enhanced in infiltrated BALF cells in steroid-resistant asthmatics." (PMID 31779093, 2019). "Although not studied in asthma, low-dose IL-2 therapy has been found beneficial in patients with diseases including graft-versus-host disease, many of whom were receiving glucocorticoids, and hepatitis C virus–induced vasculitis." (PMID 30598515, 2019). "In addition to previously identified variables, the data provide further evidence for the importance of IL-2, IL-5, IL-6, IL-8, IL-10, IFN-γ, TNF, asthma, polyposis, and aspirin sensitivity, in efforts to demarcate distinct endotypes of CRS." (PMID 30283438, 2018). "Our data suggest a critical promoting effect of IL-2 on LTE4 and epithelial cytokine-induced activation of human ILC2s, which might be relevant to the pathogenesis of asthma and atopic dermatitis." (PMID 28115217, 2017). "Pathways exclusively enriched in AD included Cytokines and Inflammatory Responses, Th1/Th2 Differentiation, Dendritic Cell Pathway, Asthma, IL-12 STAT4 Signaling, CD40L Signaling, IL-4 Signaling, and CXCR3 Signaling, IL-2 STAT5 Signaling, CD8+ T-cell Signaling, and TCR Signaling." (PMID 28821884, 2017). "Regarding the mechanism of PTP-RR down-regulation, MG-132, a proteasome inhibitor, abrogated IL-2/IL-4-induced reduction of PTP-RR protein expression, suggesting that a reduction in PTP-RR protein stability in severe asthma could be taking place." (PMID 27013170, 2016). "On the other hand, the use of IL-2 alone promotes the progression of asthma rather than ameliorating it8." (PMID 27527926, 2016). "Glucocorticoids have been suggested to amplify the IL-2-dependent expansion of FOXP3+CD4+CD25+ T cells in vivo, increase FOXP3 expression by Tregs in patients affected by asthma, and restore the impaired suppressive function of Tregs in patients with relapsing multiple sclerosis." (PMID 26379673, 2015). "In line with this Interleukin-2 inhalation therapy temporarily induces asthma-like airway inflammation and daclizumab, a monoclonal antibody directed against CD25 subunit of IL2-R, improves asthma control in patients with moderate to severe persistent asthma." (PMID 26459392, 2015). "IL2 was safe in all but one patient who had an acute asthma attack after the first IL2 dose and did not receive further doses." (PMID 26413873, 2015). "IL-2, IL-4, IL-6, IL-17a and TNF-α were reported to be involved in asthma." (PMID 24735374, 2014). "Immunotherapy is used to manage IgE mediated rhinitis and asthma by down-regulation of the Th2 response by promoting a Th1 response due to production of interferon (IFN) γ, IL-2 and IL-12 and up-regulation of regulatory T lymphocytes, producing IL-10 and transforming growth factor (TGF) β." (PMID 19900263, 2009).
asthma (continued). "Previous studies have suggested that several growth factors or chemokines (eotaxins, IL-2/3/5/8, GM-CSF, and PGD2) could prime eosinophils, but it is still unclear which factor dominates the priming effect of eosinophils in asthma and if priming is reversible." (PMID 38493955, 2024). "Our findings have revealed that obese asthma patients, despite the basic anti-inflammatory therapy, had elevated levels of inflammatory markers in blood plasma such as leptin, tumor necrosis factor-α (TNF-α), interleukin-2 (IL-2), IL-4, and IL-17a, leukotriene B4 (LTB4), and thromboxane B2 (TXB2)." (PMID 37367676, 2023). "Given that VSTM4 reduces IFN-γ and IL-2 produced by T cells and inhibits naïve CD4+T cell differentiation into Th1 cells, VSTM4 may contribute to a relative predominance of Th2 inflammation over Th1 inflammation in asthma." (PMID 36076228, 2022). "Early studies in patients with mild asthma have shown that CD4+ T cells favour Th2 type immune responses in BALF, lung tissue, and blood, and secrete large amounts of cytokines, such as IL‐4, IL‐5, IL‐13 and IL‐9, while Th1‐type cytokines such as IFN‐γ, IL‐2 and IL‐12 are reduced." (PMID 33124760, 2020). "Our data suggest that aberrant glucocorticoid-driven IL-17A in SR asthma may be a result of the immune environment in these patients, and, in particular, low, but not absent, levels of IL-2." (PMID 30598515, 2019). "Though our study was not designed to examine steroid‐resistant asthma per se, which involves assessment presteroid/poststeroid treatment as in Ref.52 we did observe that patients with higher inhaled steroid requirements produced more IL‐2." (PMID 30994266, 2019). "However, in PBMCs from asthma patients the increase in IFNγ correlated significantly with IL-2 (ρ = 0.648 p<0.05), but not with IL4 or IL-13, showing a Th1 dominant shift in response to sitostanol." (PMID 23091602, 2012). "Because signalling by IL-15 occurs via the IL-2/IL-15 receptor β-chain (CD122) and common γ chain receptor (CD132) expressed primarily by NK and memory CD8 T cells, it will be of great interest to determine the levels of these receptors on airway NK and CD8 T cells in virus-induced asthma." (PMID 21779162, 2011). "In asthmatic children without RV infection, the concentrations of non-Th2 cytokines (IL-2, IL-8, TNF-α, and IFN-γ) were not significantly different between mild, moderate, or severe asthma measured by Pediatric Asthma Score (PAS)." (PMID 30210646, 2018). "IFN-gamma and IL-2 levels were significantly increased in BALF with Dexamethasone, but not with PI3K inhibitor in asthma." (PMID 28293189, 2017). "CD8-depleted PBMCs were isolated from 12 patients with SS and 23 patients with SR asthma and cultured for 7 days with anti-CD3 and IL-2 with or without dexamethasone." (PMID 25772594, 2015). "Corrigan has shown enhanced interleukin-2 (IL-2) and human leukocyte antigen (HLA-DR) receptor expression on peripheral T lymphocytes in GCR as opposed to GC sensitive (GCS) asthma." (PMID 21206697, 2010). "Children with asthma had higher levels of IL-2 (p = 0.005), IL-5 (p < 0.001), IL-13 (p = 0.021), IL-17A (p < 0.001), IL-22 (p < 0.001), IL-33 (p < 0.001), TNF-α (p < 0.001), and lower levels of IL-10 (p = 0.046) and leptin (p < 0.001) compared to those without asthma." (PMID 39902293, 2024). "We tested this hypothesis by comparing plasma cytokines, including IL-2, IL-5, IL-10, IL-13, IL-17A, IL-22, IL-33, IFN-γ, and TNF-α and the adipokine, leptin in normal weight and overweight/obese children, both with and without asthma in a cross-sectional study." (PMID 39902293, 2024).
diabetes (133 papers, 2006 to 2025). "Data obtained in this study show that the transition from prediabetes to diabetes in NOD mice is associated with the decrease in IL-2-producing ILC3 and FoxP3+ Treg in the SILP." (PMID 37110604, 2023). "In our study, we found that the induction of diabetes was associated with decreased levels of IL-2, IL-7, and IL-4, which reflects perturbations in adaptive immunity." (PMID 35554836, 2022). "STZ-induced diabetes was associated with increased levels of blood glucose, ROS, and IL-6 and decreased levels of IL-2, IL-7, IL-4, and GSH." (PMID 35554836, 2022). "It has already been reported that Tregs from patients with diabetes exhibit deficient IL-2 production and/or signaling, and if the IL-2 pathway is blocked, the frequency of Tregs decreases, and the number of individuals affected by T1D increases." (PMID 33604389, 2021). "Variants in the IL-2 gene predisposed to diabetes by reducing IL-2 production, which in turn impaired a feedback mechanism involving in Treg activity." (PMID 29033948, 2017). "Diabetes susceptibility in NOD mice was reversed by treatment with IL-2, with increased Treg numbers and function." (PMID 29033948, 2017). "Here the authors show that autoreactive anti-IL-2 T and B cells are present in type 1 diabetes patients, and that anti-IL-2 antibodies precede diabetes onset in mice, suggesting their potential as a diagnostic marker." (PMID 27708334, 2016). "Recent studies have identified defects in IL-2R signaling in T1D patients and the diabetes susceptibility locus, Idd3, which contains IL-2 was recently shown to control Treg function through an effect on APC." (PMID 24367363, 2013). "Additionally, elevated levels of HDL and IL-2 were positively associated with diabetes in stroke patients (HDL: P = 0.004, χ2 = 9.210; IL-2: P = 0.001, χ2 = 12.313)." (PMID 38287458, 2024). "Deficiency in IL-2, which is the activator of Tregs, explains the dysfunction in diabetes." (PMID 36768715, 2023). "Additionally, it has been established that the induction of diabetes in animal models is associated with perturbations in the levels of different cytokines, including IL-2, IL-7, and IL-4, which can perturb adaptive immunity." (PMID 35554836, 2022). "Notably, for plasma, stable analytes included the cytokines IL-1Ra and IL-2, and diabetes-associated proteins, such as C-Peptide, ghrelin and leptin." (PMID 33753773, 2021). "This is important because it is still unclear whether defects in the IL2/IL2R pathway play a significant role in most cases of human diabetes; although a gene variant of IL2RA (CD25) has been associated with T1D risk in people, it is protective but rare." (PMID 29527189, 2018). "IL-2 is a diabetes-associated gene located within the Idd3 loci." (PMID 26124756, 2015). "Thus, mouse and rats’ susceptibility to develop STZ-induced type 1 DM and susceptibility of NOD and BB animals to develop diabetes is closely related to the higher levels of IL-2, IFN-γ, and TNF-α production by infiltrating macrophages and T cells and other cells." (PMID 28824543, 2017). "Another consideration is the finding in individuals with diabetes that, although low-dose IL-2 expands the Treg compartment, the numbers of NK and CD8+ T cells are increased." (PMID 40133487, 2025). "IL-2 has been reported to remain elevated following bariatric surgery in patients with diabetes, despite improved glycemic control." (PMID 41030257, 2025). "Nevertheless, low-dose IL-2 is well tolerated in individuals with diabetes, with side-effects being limited to infection at the injection site." (PMID 40133487, 2025). "iNKT cells activate various immune cells by secreting cytokines like interferon-γ (IFN-γ) and interleukin-2 (IL-2) to exert diverse biological functions, including anti-tumor, anti-viral, anti-obesity, and anti-diabetes activities." (PMID 39221140, 2024). "Administration of low-dose IL-2 promoted Tregs survival and protected mice from developing diabetes." (PMID 39000278, 2024).